LRRC15 (leucine rich repeat containing 15)
Diseases named in the same sentence as LRRC15 in open-access papers (continued):
Sharing a sentence is not in itself a finding about the gene and the disease.
metastatic disease (1 paper, 2025). "The upregulation of genes encoding matrix associated factors including proteases and cell adhesion molecules such as ADAM12, NTN3, LRRC15, CDH17, PCDH19, VTN highlighted the relevance of the tumor microenvironment and cell–cell and cell–matrix interaction for progression to metastatic disease." (PMID 41402347, 2025).
myxofibrosarcoma (1 paper, 2020). A malignant fibroblastic neoplasm arising from the soft tissue. "The proportion of LRRC15-positive cases among myxofibrosarcomas was significantly lower in comparison to other histological subtypes such as UPS (19%, p < 0.0001)." (PMID 32210091, 2020). "For instance, 50% of UPS expressed LRRC15 versus 19% only for myxofibrosarcoma." (PMID 32210091, 2020).
oligoarticular JIA (1 paper, 2022). "LRRC15, GREM1, and GREM2 are overexpressed in chondrocyte-like cells from persistent oligoarticular JIA FLS compared to pre-extension oligoarticular JIA FLS." (PMID 36167601, 2022).
oral cancer (1 paper, 2024). "The ECM immunoreaction with LRRC15 also indicated that this protein was soluble and released from cellular components, especially the “oral cancer tissue” portion." (PMID 39457685, 2024).
osteoporosis (1 paper, 2018). A condition of reduced bone mass, with decreased cortical thickness and a decrease in the number and size of the trabeculae of cancellous bone (but normal chemical composition), resulting in increased fracture incidence. "Both in-vitro and in-vivo experiments suggested that LRRC15 might function as a target for the treatment of metabolic bone disease such as osteoporosis through governing MSC fate." (PMID 29523191, 2018).
ovarian serous cystadenocarcinoma (1 paper, 2025). A malignant serous cystic epithelial neoplasm arising from the ovary. "For ovarian serous cystadenocarcinoma (PDC000362), LRRC15 was validated as a metastasis-associated protein with significant overexpression in intestinal metastases." (PMID 40597613, 2025).
pterygium (1 paper, 2022). A wedge-shaped fibrovascular lesion arising from the bulbar conjunctiva and extending to the cornea. "Among those DE-mRNAs, matrix metallopeptidase 3(MMP-3), fibronectin 1 (FN1), tenascin C (TNC), LRRC15, KRT6A, COMP, AKR1B10, and MUC5AC were significantly upregulated, which was consistent with previous studies on pterygium." (PMID 36398070, 2022).
serous ovarian cancer (1 paper, 2023). "The LRRC15 signature can be used to predict the clinical prognosis and primary platinum resistance of high-grade serous ovarian cancer patients." (PMID 36653841, 2023).
systemic sclerosis (1 paper, 2025). A chronic disorder, possibly autoimmune, marked by excessive production of collagen which results in hardening and thickening of body tissues. "The insights from this study pave the way for future investigations into the therapeutic potential of selectively targeting LRRC15 in the context of systemic sclerosis and cancer." (PMID 41008788, 2025).
cancer (64 papers, 2017 to 2025). A tumor composed of atypical neoplastic, often pleomorphic cells that invade other tissues. "A specific subpopulation of cancer-associated fibroblasts, defined by LRRC15 expression, suppresses cytotoxic CD8+ T cells." (PMID 39837478, 2025). "We also demonstrate for the first time that LRRC15, a protein previously associated with myofibroblast transformation of cancer-associated fibroblasts, is also expressed by corneal myofibroblasts." (PMID 38994947, 2024). "The TCGA-GTEx analysis results showed that only LRRC15 was highly expressed in both cancer-associated fibroblasts (CAFs) and the tumour stroma of OC and was related to clinical prognosis." (PMID 36653841, 2023). "In line with the frequent LRRC15 expression in SCC cancer-associated fibroblasts (81% of cases), an anti-LRRC15 MMAE-conjugated ADC, ABBV-085, triggered complete response in SCC xenograft (PDX) models." (PMID 35159045, 2022). "LRRC15-positive cancer-associated fibroblasts constitute a pivotal axis in tumorigenesis and are potential therapeutic targets to improve responses to immune checkpoint blockade." (PMID 36171287, 2022). "The S2d SFs also express Lrrc15, a recently identified marker for cancer-associated fibroblasts (CAFs) and activated fibroblasts and the TF Runx1." (PMID 35879783, 2022). "Recent studies have highlighted LRRC15 expression targeting mesenchymal cells and cancer-associated fibroblasts (CAF)." (PMID 36293532, 2022). "LRRC15 is a leucin-rich repeat domain-containing protein, which is an orphan cancer-associated protein." (PMID 36228039, 2022). "The human leucine-rich repeat-containing protein 15 (LRRC15) is a membrane protein identified as a marker of CAF (cancer-associated fibroblast) cells whose overexpression is positively correlated with cancer grade and outcome." (PMID 36293532, 2022). "LRRC15 is a new cancer-associated fibroblast and mesenchymal marker that is overexpressed in OS tissue samples and is being investigated as a potential therapeutic target for ADC-based sarcoma treatment." (PMID 35311145, 2022). "Leucine-rich repeat containing 15 (LRRC15) is a type I membrane protein with low expression in normal tissue but is highly expressed on cancer associated fibroblasts within the tumor stroma as well as directly on cancer cells including GBM." (PMID 34926242, 2021). "LRRC15 is overexpressed in cancer-associated fibroblasts and cancer cells from many epithelial and mesenchymal solid tumors." (PMID 34440182, 2021). "Notably, although LRRC15+ myofibroblasts have also been implicated in antiviral and antifibrotic processes, they are specifically known for their link to cancer." (PMID 41438752, 2025). "LRRC15, a type I membrane protein comprising 581 amino acids with no obvious intracellular signaling domains, is upregulated by the proinflammatory cytokine TGFβ in cancer-associated fibroblasts." (PMID 38827307, 2024). "Leucine-rich repeat containing 15 (LRRC15) is a marker of cancer-associated fibroblasts." (PMID 35159045, 2022). "In preclinical studies, samrotamab vedotin extended event-free life in patient-derived xenograft (PDX) models, which may target cancer cells over LRRC15-positive cancer-associated fibroblasts due to the cell-permeable characteristics of MMAE." (PMID 35311145, 2022). "Targeting cancer-associated fibroblasts through LRRC15 in order to reduce immunosuppressive properties of the TME could overcome therapeutic resistances." (PMID 35159045, 2022). "However, the molecular signals that underlie the development of LRRC15+ cancer-associated fibroblasts (CAFs) and their direct impact on anti-tumour immunity are uncharacterized." (PMID 36171287, 2022). "Leucine rich repeat containing 15 (LRRC15), also named LIB, is a gene encoding leucine-rich transmembrane protein that participates in the cell–matrix adhesion and cell migration, and is induced and highly expressed in various cancer types." (PMID 29137139, 2017).
cancer (continued). "Additionally, LRRC15 was considered as a new marker of cancer-associated fibroblasts and cancers of mesenchymal origin and might be applicated in antibody–drug conjugate targeting the tumor stroma." (PMID 32043519, 2020). "Leucine-rich repeat containing 15 (LRRC15) has emerged as an attractive biomarker and target for cancer therapy." (PMID 41022704, 2025). "This co-localization suggests cellular internalization of the antibody after binding with LRRC15 on the plasma membrane of both cancer and stromal cells." (PMID 41022704, 2025). "Having demonstrated the significant therapeutic potential of our radioimmunotheranostic platform, we sought to understand the molecular effects of LRRC15-targeted RIT on cancer cells and the tumor microenvironment." (PMID 41022704, 2025). "In particular, FN1, VCAN, and LRRC15 are markers of BMSCs which also co-modularized with COL10A1 in cancer; all three genes are involved in cell migration, and FN1 contributes directly to osteoblast mineralization as well as metastasis." (PMID 39939916, 2025). "They identified LRRC15 as a marker of TGFβ-driven myoCAFs, which were the dominant fibroblasts in advanced tumors across multiple human cancer types." (PMID 40469190, 2025). "The majority of in vitro myCAFs were present in cluster 2, which contained the cancer-specific LRRC15+ CAFs from in vivo." (PMID 40215177, 2025). "LRRC15 shows highly restricted expression in some pro-tumorigenic and immunosuppressive CAFs; therefore, it has become a good cancer-specific antigen for therapeutic targeting." (PMID 40469190, 2025). "Regarding LRRC15, the cancer stroma displayed a diffuse immunoreaction, whereas scarce immunoreaction was observed in the normal oral mucosa connective tissue." (PMID 39457685, 2024). "Meanwhile highly enriched cancer-associated fibroblasts (CAF) signatures can also be observed in subtype A tumors, especially for pan-CAF (pCAF), desmoplastic CAF (dCAF) and LRRC15 + CAF." (PMID 39060379, 2024). "In cancer, the differentiation of fibroblasts into LRRC15 myofibroblasts is carried out through TGFβ signaling." (PMID 38994947, 2024). "Recent studies have identified a TGF-β–driven, LRRC15+ CAF lineage that suppresses antitumor immunity and is associated with poor response to a-PD-1 in several malignancies." (PMID 39298276, 2024). "The largest group of TAAs (n = 14) derived from genes reported as markers of cancer-associated fibroblasts (CAFs) (COL11A1, COL10A1, LRRC15)." (PMID 37906288, 2024). "Unlike CTHRC1, LRRC15 is a cell surface marker, and an antibody drug conjugate against LRRC15 is currently under clinical development to target cancer stromal cells." (PMID 37311583, 2023). "Pan-cancer analysis revealed that LRRC15 and LRRC32 are differentially expressed in multiple cancers." (PMID 36653841, 2023). "These human data reveal a central axis of CAF heterogeneity across human cancers defined by universal fibroblasts and LRRC15+ myofibroblasts, with TGFβ signalling enriched in indications in which LRRC15+ CAFs are abundant." (PMID 36171287, 2022). "In this study, we provided direct genetic evidence that TGFβ signalling in DPT+ universal fibroblasts promotes LRRC15+ myofibroblast formation during tumorigenesis, constituting a central fibroblast axis in multiple human cancers." (PMID 36171287, 2022). "ABBV-085 has demonstrated significant antitumor activity in multiple LRRC15 cancer-positive models, including GBM." (PMID 34926242, 2021). "Lrrc15 expression is restricted to the placental cytotrophoblast during development but upregulated in invasive cancer cells and stimulated by inflammatory cytokines in adult tissues." (PMID 34702854, 2021). "In particular, it was reported that OS tissue samples had high LRRC15 expression both on cancer and stroma cells." (PMID 34440182, 2021). "Consistent with these first results, we found LRRC15 to be expressed by cancer cells in up to 36% of STS with significant differences across histological subtypes." (PMID 32210091, 2020).
cancer (continued). "In contrast to the patterns observed in epithelial tumors, LRRC15 was expressed not only by normal stromal (predominantly fibroblasts) cells but also by cancer cells." (PMID 32210091, 2020). "The tumor antigen 15-leucine-rich repeat containing membrane protein (LRRC15) is a transmembrane protein demonstrated to play important roles in cancer." (PMID 29523191, 2018). "Notably, we demonstrated that ENG+ CAFs, WT1+ CAFs, and CAPs shared phenotypic characteristics with mesenchymal populations in the healthy developing pancreas, whereas LRRC15+ CAFs represented a cancer-specific phenotype." (PMID 40215177, 2025). "Interestingly, Lrrc15 and Tgfb1 levels in HCC1954 stroma remained constant, while TGFB1 expression was increased in treated LRRC15-null HCC1954 cancer cells." (PMID 41022704, 2025). "Recently, myofibroblast populations identified in cancer have been characterized by the expression of the leucine-rich repeat containing protein 15, LRRC15, and are known as LRRC15 myofibroblasts, which share many similarities to corneal myofibroblasts observed during wound healing." (PMID 38994947, 2024). "Additionally, a distinctive and diffuse immunoreaction of LRRC15 was observed in the cancer stroma, suggesting that PD-CAFs and ECM are immuno-positive for LRRC15." (PMID 39457685, 2024). "Interestingly, LRRC15, a protein previously identified in cancer myofibroblasts, was highly expressed in corneal myofibroblasts, both with and without vimentin." (PMID 38994947, 2024). "Furthermore, in immunotherapy clinical trials involving more than 600 patients with six kinds of cancer, LRRC15 + CAF displayed signal levels with anti-PD-L1, indicating a poorer response to treatment." (PMID 36653841, 2023). "In the rat glia cell line C6, LRRC15 is mildly regulated in response to proinflammatory cytokines like IL1β, IL6, and TNFɑ, and more recently TGFβ signaling has been linked to LRRC15 expression in cancer-associated fibroblasts." (PMID 36757924, 2023). "Clinically, high expression of a LRRC15+ CAF gene signature in bulk RNA-seq data from patients with cancer was associated with a lack of response to anti-programmed death ligand 1 (PDL1) ICB1." (PMID 36171287, 2022). "Next, we aimed to understand whether the axis between universal fibroblasts and LRRC15+ myofibroblasts was representative of the fibroblast compartment in human cancers." (PMID 36171287, 2022). "Furthermore, clinical trials of immunotherapy in several cancer types, including bladder cancer, and non-small cell lung cancer, have shown that elevated levels of a LRRC15 + CAF signature correlated with poor response to anti-PD-L1 therapy." (PMID 36010986, 2022). "Additionally, they also found that myCAFs cluster surrounds the cancer islet and promotes expression of leucine-rich repeat containing 15 (LRRC15)." (PMID 33599893, 2021). "LRRC15, a 581 amino acid type I membrane protein with no obvious intracellular signaling domains, has recently been reported as a marker of cancer-associated fibroblasts." (PMID 32210091, 2020). "Moreover, ABBV-085, a monomethyl auristatin E (MMAE)-containing antibody–drug conjugate (ADC) designed to target against LRRC15, has shown significant anti-tumor activity in several LRRC15 stromal-positive or cancer-positive models." (PMID 32210091, 2020). "AREG and NRG1 expressions in cancer stroma were not closely associated with CAFGs (LRRC15, R = 0.04 and 0.03, respectively) at all, suggesting that EGFR ligands-expressed CAFs may be unique subpopulations among CAFs." (PMID 38892190, 2024). "We evaluated the predictive performance of HYP.SIG by comparing it with established pan-cancer models for ICI response prediction, including INFG.Sig, T.cell.inflamed.Sig, PDL1.Sig, NLRP3.Sig, LRRC15.CAF.Sig, and Cytotoxic.Sig." (PMID 41419193, 2025). "We assessed the mRNA expression levels of LRRC15, EFNA3, TSPAN13, and CA12 in diverse cancer tissues and compared them to normal tissue using the TIMER2.0 database." (PMID 38611080, 2024).
cancer (continued). "Taken together, these findings suggest that LRRC15, EFNA3, TSPAN13, and CA12 can serve as potential biomarkers for improving cancer diagnosis screening and as suitable targets for therapy with reduced side effects and enhanced efficacy." (PMID 38611080, 2024). "The leucine‐rich proteins, including small leucine‐rich proteoglycans, LRRC15 and basic leucine zipper transcription factor, NRF2, have emerged as novel therapeutic targets against cancer." (PMID 37983928, 2023). "Compared with pan-cancer signatures (INFG.Sig, T.cell.inflamed.Sig, PDL1.Sig, LRRC15.CAF.Sig, NLRP3.Sig, and Cytotoxic.Sig), Stem.Sig showed best performance in the testing set with an AUC of 0.71, followed by INFG.Sig with an AUC of 0.66." (PMID 35488273, 2022). "Another study revealed that the infiltration of CAFs expressing leucine-rich repeat-containing 15 (LRRC15), whose expression was induced by TGF-β, correlated with poor response to ICB therapy across multiple cancer types." (PMID 35236758, 2022). "ABBV-085’s unique mechanism of action relied upon the ability of LRRC15-specific mAb to localize the MMAE payload at high levels in the TME and the cell-permeable properties of MMAE to diffuse into nearby cancer cells and ultimately, induce tumor shrinkage." (PMID 34206707, 2021). "ABBV-085 is a monomethyl auristatin E (MMAE)-containing antibody-drug conjugate directed against LRRC15, and ABBV-085 inhibits cancer cells tumor xenograft growth." (PMID 33572223, 2021). "Importantly, the overexpression of LRRC15, EFNA3, TSPAN13, and CA12 was observed in tissues at both early and advanced stages of cancer, indicating that these proteins hold promise as targets for early diagnosis." (PMID 38611080, 2024). "Intriguingly, we found that none of the major cancer cell subclusters (Ep_TRIM54, Ep_VGLL1, and Ep_KRT6A) exhibited preferences for Fb_LRRC15." (PMID 38297291, 2024). "It is remarkable to note that the cells which transformed into myofibroblasts in our study were not derived from any cancer lineage, suggesting for the first time that LRRC15 is more universal and not just restricted to cancer fibroblast lineage." (PMID 38994947, 2024). "We demonstrated that CSFs could be potential targets for cancer treatment, and membrane molecules FAP, LRRC15, ITGA11 and SPHK1 could be used as CSFs specific targets." (PMID 36744260, 2023). "Therefore, we analysed the relationship between LRRC15 and the infiltration of various immune cells in the TIMER2.0 database using EPIC (Estimating the Proportions of Immune and Cancer cells)." (PMID 36653841, 2023). "Membrane molecules LRRC15, ITGA11, SPHK1 and FAP could be used as therapeutic targets for CSF-targeting cancer treatment." (PMID 36744260, 2023). "In animals, the actions of LRRC15 are still poorly understood, however, in humans, cancer-damaged tissues had higher expression of this gene than normal tissues." (PMID 32379844, 2020). "Nonetheless, FAP and LRRC15-targeted therapies that focus on CAFs alone may not be sufficient for cancer therapy." (PMID 41228205, 2025). "Additionally, our observations revealed that HCC1954 tumor cells predominantly maintained an epithelial phenotype, consistent with the absence of LRRC15 expression in the cancer cells." (PMID 41022704, 2025). "We found that LRRC15, ITGA11 and SPHK1 were also specifically expressed on CSFs, but not in other clusters of fibroblasts, indicating that they could also be attractive CSFs specific targets for cancer treatment." (PMID 36744260, 2023). "Overall, and in line with LRRC15 protein levels, LRRC15 expression was higher in HuO9 than in U118MG cancer cells, and not quantifiable in HCC1954 cancer cells." (PMID 41022704, 2025). "Given the lack of target expressing cancer cells, the response of HCC1954 tumors to [177Lu]Lu-DUNP19 is reliant on targeting of LRRC15+ murine CAFs." (PMID 41022704, 2025).